RNU2-51P (RNA, U2 small nuclear 51, pseudogene)
Gene: Small nuclear RNA gene on chromosome 14 (70,360,892 to 70,361,088, forward strand). Ensembl gene ENSG00000222640.
Homologues: Orthologues: chimpanzee U2 (99% identical), macaque U2 (86% identical), dog U2 (62% identical), mouse Gm25106 (49% identical), pig U2 (25% identical). Paralogues in human: U2 (75% identical), RNU2-6P (73% identical), RNU2-26P (72% identical), RNU2-2 (71% identical), RNU2-56P (71% identical), RNU2-57P (71% identical), U2 (71% identical), RNU2-52P (70% identical), RNU2-64P (70% identical), RNU2-68P (70% identical), RNU2-48P (70% identical), RNU2-3P (69% identical), and 66 more.